HMGB1 (high mobility group box 1)
Diseases named in the same sentence as HMGB1 in open-access papers (continued):
Sharing a sentence is not in itself a finding about the gene and the disease.
tumor (continued). "The damage-associated molecular patterns (DAMPs) are released by dying tumor cells, which primarily consist of CRT, HMGB1, and ATP." (PMID 38868091, 2024). "It has been shown that tumor-expressed high mobility group box-1 (HMGB1) also enhances MDSCs-mediated downregulation of L-selectin on naive T cells." (PMID 38609997, 2024). "Serum HMGB1, which increased in tumor-bearing rats, was reduced to one-tenth with BBR treatment, while TNFα reduced by one-third." (PMID 38731953, 2024). "HMGB1 is a histone-chromatin binding protein released after tumor cells are damaged by radiation and undergo apoptosis." (PMID 39231199, 2024). "Through the cGAS-STING pathway, DAMPs, such as calreticulin, ATP, and HMGB1, promote DCs and macrophages’ recognition of tumor antigens and facilitate the infiltration of CD8+T cells into tumors, thereby stimulating tumor immunity." (PMID 38853203, 2024). "Cell activity was observed by plotting cell growth curve, the result showed that tumor cell viability of 143B cells decreased after siACTB treatment and increased after HMGB1 treatment." (PMID 38649690, 2024). "The release of HMGB1 can further trigger the expression of CD274 (PD-L1) in tumor cells and inhibit T cell immune function." (PMID 39314628, 2024). "HMGB1 and ATP release are also known as danger signals that can stimulate phagocytosis of dying tumor cells by DCs and macrophages." (PMID 38560565, 2024). "To assess the impact of inhibiting GPR65 or HMGB1 on tumor progression in an in vivo context, we subcutaneously injected U87 cells, with or without tumor-associated macrophages (TAMs), into nude mice to establish subcutaneous xenograft tumors." (PMID 38576043, 2024). "The expression of HMGB1 in tumor tissues after drug treatment in each group was further detected by immunofluorescence." (PMID 39014462, 2024). "During tumor development, intracellular HMGB1 acts as an antitumor protein to maintain genomic stability and autophagic activity." (PMID 37897664, 2024). "HMGB1 is involved in tumor progression as a pro-inflammatory and protumor cytokine released by necrotic cells." (PMID 38725632, 2024). "In tumor immunotherapy, blocking the expression of extracellular HMGB1 can improve the efficacy of anti-PD-1 tumor immunotherapy." (PMID 39314628, 2024). "In conclusion, HMGB1 plays a crucial role in tumor angiogenesis by activating various signaling pathways and inducing the production of angiogenic factors." (PMID 38725632, 2024). "Directional migration and invasiveness of tumor cells is enhanced by the CXCL12/HMGB1 heterocomplex, and is CXCR4 dependent." (PMID 38803493, 2024). "Specifically, alterations in cytokines such as IL32, IL22, IL17F, IL17A, IL16, IL15, and HMGB1 can create an immunosuppressive tumor microenvironment in CTCLs to facilitate immune evasion and tumor progression." (PMID 39409988, 2024). "HMGB1 has been reported to play a crucial role in maintaining the structure and function of chromosomes and is released by ferroptotic tumor cells in an autophagy-dependent manner." (PMID 38292937, 2024). "HMGB1 regulates cellular death and survival pathways, as well as contributes to various stages of tumor progression, including proliferation, invasion, and metastasis." (PMID 38725632, 2024). "For example, in CRC, the release of the High Mobility Group Box 1 protein (HMGB1) from tumor cells affects host energy metabolism and induces muscle autophagy." (PMID 39706853, 2024). "High levels of HMGB1 and RAGE expression in tumors are associated with poor prognosis, suggesting a role of HMGB1/RAGE axis in tumor prognosis." (PMID 38529373, 2024). "To elucidate the pivotal role of HMGB1 in CMs derived from lactate-stimulated TAMs, we introduced recombinant HMGB1 (rHMGB1) as a supplement into CMs from shGPR65 TAMs to stimulate tumor cells." (PMID 38576043, 2024).
tumor (continued). "Resveratrol induces immunogenic cell death by increasing CRT and HMGB1 expression in ovarian cancer cells, reducing tumor volume, suppressing TGF-β, and boosting IL-12 and IFN-γ levels." (PMID 39519572, 2024). "An early study also found that High Mobility Group Box 1 (HMGB1) released by ferroptosis cells in an autophagy-dependent manner can also enhance anti-tumor immunity." (PMID 39769097, 2024). "It has been found that the interaction of TIM3 and HMGB1 on dendritic cells (DCs) can suppress the innate immune response to nucleic acids in the tumor environment." (PMID 39759854, 2024). "Tumor immunotherapy has evolved into one of the most effective treatments, with the role of HMGB1 in anti-tumor immunity also becoming a focal point of research." (PMID 37897664, 2024). "Accordingly, we demonstrated herein that NExT are naturally functionalized with diverse receptors (PD1, LAG3, TIM3) that can interact with their corresponding ligands (e.g., PDL1, Galectin-3, FGL-1, MHCII, Galectin-9, HMGB1, Ceacam-1) within the tumor." (PMID 38730475, 2024). "Hydrogel/CN-Pt/GEM + NIR-treated tumor cells showed the highest HMGB1 expression and ATP secretion among the tested groups." (PMID 38902678, 2024). "In vitro, NanoCD-treated B16F10 cells released DAMPs associated with anti-tumor immunity, including uric acid, ATP, calreticulin (CRT), and HMGB1." (PMID 38391959, 2024). "Patients with high HMGB1 expression had significantly poorer response to chemoradiation assessed by tumour reduction ratio and regression grade." (PMID 38353760, 2024). "In particular, the nuclear protein high-mobility group box 1 (HMGB1) seems to be an endogenous stimulus produced by tumor cells that mediates the induction of NETosis in C5a-stimulated polymorphonuclear MDSCs (PMN-MDSCs)." (PMID 38339243, 2024). "The chronology of DAMP emission demonstrated by HG-3 and OSU-CLL cells subjected to SpiD3 treatment—starting with ecto-CALR, followed by extracellular ATP and HMGB1 release—is concordant with studies in the literature characterizing ICD in other tumor models." (PMID 39767763, 2024). "ES-Cu-MOF significantly escalated mitochondrial oxidative stress in cellular models, facilitating the release of DAMPs such as CARL and HMGB1 from dying tumor cells." (PMID 38938647, 2024). "Correspondingly, when HMGB1 is knocked out, the sensitivity of tumor cells to chemotherapy can be enhanced, leading to chemotherapy-induced apoptosis." (PMID 37897664, 2024). "Calreticulin, which is upregulated by radiation, acts as a pro-phagocytosis “eat-me” signal, while HMGB1 released from tumor cells promotes antigen presentation by DCs via TLR4 activation." (PMID 39228005, 2024). "The tumor microenvironment also releases cytokines including calreticulin (CRT), high-mobility group box 1 (HMGB1), adenosine triphosphate (ATP), and tumor-associated antigens, inducing immunogenic cell death (ICD)." (PMID 38673726, 2024). "The high-mobility group box 1 (HMGB1) protein can be released extracellularly in tumor cells with ferroptosis and act as a kind of DAMP to bind with receptors such as RAGE and TLR2, thus inducing immune cell activation coupled with the generation of cytokines." (PMID 38443363, 2024). "HMGB1 binds to advanced glycosylation end product‐specific receptor (AGER) to release TNF‐α synergistically for anti‐tumour immunotherapy." (PMID 38652105, 2024). "Our prior investigation revealed that HMGB1 expression on tumor-derived exosomes accelerates the accumulation of TIM-1+ Breg cells." (PMID 38755598, 2024). "The increased secretion of HMGB1 following tumor cell apoptosis also promotes the activation of DCs and the presentation of tumor antigens." (PMID 38835772, 2024). "Our recent study demonstrated that FBP can inhibit tumor growth and enhance the sensitivity of tumors to chemotherapy by directly binding to HMGB1." (PMID 39693295, 2024).
tumor (continued). "In the mouse xenograft model, tumors in the HMGB1 knockdown group were noticeably smaller, and tumor growth was significantly slower." (PMID 39717781, 2024). "In summary, HMGB1 is not only a biomarker for prognostic analysis and immunotherapy response but also a potential target for tumor therapy." (PMID 37897664, 2024). "This anti-tumor response from ferroptotic hepatocytes was counterbalanced by the simultaneous release of HMGB1, a cellular DAMP, from tumor cells." (PMID 38540172, 2024). "Summarize all, the tumor-promoting effects of lactate stimulated TAMs were mediated by GPR65 through the secretion of HMGB1." (PMID 38576043, 2024). "It has been reported that HMGB1 can be secreted extracellular by ESCC cells in the form of exosomes to promote the proliferation of tumor cells." (PMID 39314628, 2024). "Following treatment, calreticulin exposure on the cell membrane peaked at 6 h, and the levels of ATP and HMGB1 increased significantly, indicating that combination therapy induces immunogenic cell death, thereby inhibiting tumor recurrence and metastasis." (PMID 39735534, 2024). "HMGB1 in the tumor microenvironment activates MDSCs via the NF-κB signaling pathway, and MDSCs produce high levels of immunosuppressive molecules (such as IDO) that inhibit T cell function." (PMID 39314628, 2024). "Extracellular HMGB1 inhibition by glycyrrhizic acid efficiently boosted anti-PD-1 efficacy by remodeling the tumor microenvironment." (PMID 39354529, 2024). "Consistently, the highest amount of HMGB1 was observed in tumor slices treated with both cisplatin and MβCD." (PMID 39343834, 2024). "Under stress conditions, tumor cells release altered EVs with a distinct molecular composition, carrying molecules like HMGB1, HSPs, ATP, and mitochondrial DNA, which create an inflammatory environment that aids in immune recognition of the tumor." (PMID 39062046, 2024). "Regarding tumor angiogenesis, inhibiting the HMGB1/RAGE axis leads to a decrease in the expression of vascular endothelial growth factor (VEGF) and its receptor VEGFR2, thereby inhibiting tumor angiogenesis." (PMID 38529373, 2024). "The production of high levels of HMGB1 by tumor cells, as well as by infiltrating inflammatory cells, favors the establishment of a highly immunosuppressive tumor microenvironment." (PMID 39830522, 2024). "Our study examined the expression patterns of ICP like PD-L1 and TIM-3 and ICD modulators like CALR and HMGB1 in two ferroptosis subtypes to determine their effects on host anti-tumor immunity and mRNA vaccine efficacy." (PMID 39286654, 2024). "The role of HMGB1 in cancer is intricate, with implications for tumor development, progression, metastasis, and the response to chemotherapeutics involving both intracellular/nuclear and extracellular forms of HMGB1." (PMID 38469295, 2024). "Immunohistochemical staining was used to evaluate the cytoplasmic expression of HMGB1 in tumor tissues after different treatments." (PMID 38384466, 2024). "During the ICD process, the translocated HMGB1 couples with TLR4 on the surface of DCs to improve the efficient processing and cross-presentation of tumor-associating antigens before apoptosis, thereby activating specific T-cell immune responses." (PMID 39916954, 2024). "This activation involves the release of DAMPs, such as calreticulin (CALR), HMGB1, adenosine triphosphate, and HSPs, from dead tumor cells." (PMID 38725632, 2024). "Overall, these results suggest that HMGB1 plays a critical role in tumor cell proliferation, apoptosis, and tumor growth, further supporting its importance as a Necroptosis.Sig modeling gene in tumor development and immune evasion." (PMID 39717781, 2024). "We observed that PRKN expression depleted the cellular content of the alarmin and potent DAMP, High Mobility Group Box 1 (HMGB1) in multiple tumor cell types, compared with control cultures." (PMID 39213189, 2024).
tumor (continued). "Previous studies have shown that ICP regulators, such as PD-L1 and TIM3, and ICD regulators, such as CALR and HMGB1, play critical roles in regulating host anti-tumor immunity and thus affect the efficacy of mRNA vaccines." (PMID 38672082, 2024). "In terms of tumor autophagy, the HMGB1/RAGE axis induces cellular autophagy through signaling pathways involving PI3K-AKT-MDR1, mTOR, NF-kB, MAPK, and p-ERK1/2." (PMID 38529373, 2024). "HMGB1 increases the number of immunosuppressive cells, such as Tregs, thereby inhibiting anti-tumor immune responses." (PMID 39507236, 2024). "In terms of tumor proliferation, the HMGB1/RAGE axis promotes tumor cell growth through several signaling pathways, including NF-kB, K-Ras, MAPK, AKT, mTOR, STAT3, MEK, and ERK1/2." (PMID 38529373, 2024). "HMGB1 is not only linked to ICD but can also be increased in several stress conditions such as therapy-related inflammation and neoplastic disease as such." (PMID 39572927, 2024). "It contributes to metastasis by promoting cell transformation and a supportive tumor microenvironment through ligands such as AGEs, HMGB1, and S100 proteins." (PMID 39830522, 2024). "One of the primary driving forces is the increased autophagic flux of tumor cells prompted by the high expression of extracellular HMGB1." (PMID 37897664, 2024). "Most tumours showed only nuclear staining of HMGB1 (53/65) with a smaller cohort exhibiting nuclear and cytoplasmic co-expression (12/65)." (PMID 38353760, 2024). "Our results on the cancer cell line analyzed, are in line with previous studies demonstrating that monomeric HMGB1 is expressed by tumor cells, and dimerization is only induced upon exposure to therapeutic irradiation." (PMID 38803493, 2024). "For instance, upon infection with oncolytic adenoviruses, tumor cells release DAMPs such as HMGB1 and ATP, which activate dendritic cells and promote tumor-specific T cell responses, contributing to the antitumor immune response." (PMID 38731910, 2024). "In 13 types of malignant tumors, the HMGB1/RAGE axis has been reported to promote tumor cell proliferation, and several studies have elucidated the signaling pathways involved." (PMID 38529373, 2024). "The HMGB1-RAGE pathway is vital in chronic disorders associated with oxidative stress, as well as in promoting tumor growth and invasion." (PMID 39008169, 2024). "In a mouse model of tumor vaccination, the use of HMGB1–depleted tumor cells or neutralizing HMGB1 with specific antibodies compromised the mice’s ability to fight tumor development." (PMID 38994937, 2024). "In cases of HNSCC, HMGB1 can be overexpressed in tumor cells of HNSCC, and its high levels can act as chemoattractants for Treg." (PMID 37897664, 2024). "Dying tumor cells release damage-associated molecular patterns (DAMPs), including adenosine triphosphate (ATP), calreticulin (CRT), and high mobility group box 1 (HMGB1)." (PMID 39033108, 2024). "Treatment with Sfn‐containing nanoformulations (including CS, CIS, and CISE NPs) obviously elicited CRT exposure on the surface of tumor cells and reduced extracellular release of HMGB1 compared to treatment with PBS or Sfn alone." (PMID 38884220, 2024). "Tumor-infiltrating neutrophils promote glioma progression by regulating the HMGB1/RAGE/interleukin 8 (IL8) axis." (PMID 38725632, 2024). "HMGB1 significant increase in tumor was found in the E/S Lip and P-E/S Lip groups compared with the control group." (PMID 39068444, 2024). "HMGB1 exists in multiple isoforms, including oxidized HMGB1, reduced HMGB1, sulfonyl HMGB1 and disulfide HMGB1, and these different isoforms play distinct functional roles in the tumor immune microenvironment." (PMID 38347600, 2024). "In recent years, numerous studies have investigated the pharmacological effects of HMGB1 on tumor pain and neuralgia, given its strong pro-inflammatory and propain activities." (PMID 38725632, 2024).
tumor (continued). "HMGB1 serves as a vital regulator of autophagy in tumor cells, inducing autophagy through multiple avenues." (PMID 37897664, 2024). "Collectively, the HMGB1/RAGE axis has been found to be closely related to tumor cell apoptosis, and several small-molecule chemical drugs have been reported to have anti-tumor effects by promoting tumor cell apoptosis via HMGB1/RAGE axis." (PMID 38529373, 2024). "High mobility group box 1 (HMGB1) is a nuclear DNA-binding protein with a dual role in cancer, acting as an oncogene and a tumor suppressor." (PMID 38725632, 2024). "The death of tumor cells will release tumor internal antigens, adenosine triphosphate (ATP) and high mobility group protein 1 (HMGB1) and other immune stimulators to activate the tumor immune response." (PMID 38816871, 2024). "G5‐CHC‐R+US treated group demonstrated significantly up‐regulated expression of the CRT and high mobility group box 1 (HMGB1) in tumor tissues, suggesting higher ICD‐inducing capacity." (PMID 38308196, 2024). "For instance, ferroptotic cells can release high‐mobility group box 1 (HMGB1), which activates DCs and promotes the presentation of tumour antigens to T cells, thereby enhancing anti‐tumour immunity." (PMID 39163517, 2024). "ICD refers to a mode of cell death that activates an anti-tumor immune response and is characterized by the surface or release of a number of immune-stimulating molecules, such as calreticulin (CRT), HMGB1, and ATP, from tumor cells." (PMID 38370407, 2024). "Overexpression of HMGB1 in tumor tissue can promote the proliferation and invasion of Hela cells through NF-κB signaling pathway." (PMID 39314628, 2024). "Firstly, radiotherapy can induce tumor cell death and release a series of cell factors such as HMGB1 and ATP, which can attract and activate Treg cells." (PMID 39228005, 2024). "During ICD process, the tumor release signal molecules, known as damage‐associated molecular patterns (DAMPs), including ATP, calreticulin (CRT), and high mobility group box 1 (HMGB‐1)." (PMID 38774917, 2024). "HMGB1-regulated autophagy can promote not only tumor cell proliferation but also tumor cell apoptosis." (PMID 37897664, 2024). "Significantly abundant CRT and HMGB1 fluorescence signals were detected in tumor sections after CISE‐PFD@Gel treatment, indicating that intense ICD was elicited." (PMID 38884220, 2024). "The suppression of XPO1 expression by KPT‐330 triggers the nuclear relocation of FOXO1 and HMGB1, thereby overcoming platinum resistance in tumour cells." (PMID 38783482, 2024). "HMGB1 seeks binding targets in the TME such as RAGE on tumour cells or RAGE on immune cells and TLR2/4 binding." (PMID 38652105, 2024). "As a result, the formation of the CXCL12/HMGB1 heterocomplex would be possible thanks to the release of CXCL12 by other cell types in the tumor microenvironment." (PMID 38803493, 2024). "Our findings, combined with these previous studies, showed that HMGB1 is an important intermediate molecule of IGF2BP3 induced tumor EMT and invasion/metastasis." (PMID 38504159, 2024). "MiRNA‐1284 is a tumor‐suppressor factor enhancing the antitumor activity of CP via downregulation of high mobility group box 1 (HMGB1), inhibiting apoptosis and proliferation." (PMID 38919334, 2024). "In terms of tumor apoptosis, the HMGB1/RAGE axis mediates tumor cell death through signaling pathways involving NF-kB, AKT, mTOR, and ERK1/2." (PMID 38529373, 2024). "LC3B correlated only with CD8+ cytotoxic T lymphocytes whereas, HMGB1 correlated with both local and peritumoral infiltrates involving FOXP3+ regulatory T cells and CD68+ tumor-associated macrophages." (PMID 39830522, 2024). "Compared to the findings from in vitro experiments, western blots analysis showed an enhanced ICD effect with upregulated tumor HMGB1 expression in DMPtNPS + RT group compared to other treatment groups." (PMID 38063844, 2024).